CD4 (CD4 molecule)
Diseases named in the same sentence as CD4 in open-access papers (continued):
Sharing a sentence is not in itself a finding about the gene and the disease.
tumor (continued). "Additional interactions with CTLA4, LAG3, LGALS9, and CD4 placed PD-1 at the center of a dynamic immunoregulatory network critical for tumor immune evasion." (PMID 40927719, 2025). "The LIPSTIC models have been tested in viral and tumor settings and revealed that a small fraction of hyperactivated DCs drive most of the Ag presentation to CD4+ T cells in the tumor microenvironment." (PMID 41028655, 2025). "Here, we identified cytotoxic CD4+ T cells with tumor-matching TCRs in blood that directly reflected the predominant antigenic specificities of intratumoral CD4+ T cells." (PMID 40299576, 2025). "The detailed mechanisms of A. muciniphila in regulating CD4+ T cells mediate psychological stress-induced tumor development is worth to further exploration in the future." (PMID 40038255, 2025). "Studies have analyzed tumor tissues from mouse models of B-cell lymphomas and human cases of condylomatous and follicular lymphomas, revealing high expression of OX40 and CTLA-4 on the surface of tumor-specific Tregs (CD4+, Foxp3+)." (PMID 40356928, 2025). "A single local dose of IL-12 reshaped the tumor microenvironment by reducing regulatory T cells and inducing proinflammatory macrophage and CD4+ T cell infiltration." (PMID 40895575, 2025). "Research has demonstrated that regulatory T cells can suppress the anti-cancer functions of CD8+ T cells and CD4+ T cells, thereby modulating the anti-tumor response." (PMID 40110038, 2025). "All three TCRs described by this study were derived from CD4 + T cells and this was likely to be the major factor for the limited avidity and cytotoxicity against tumor cell lines in vitro." (PMID 41410746, 2025). "T CD4 memory resting cells and M0 and M2 macrophages were found in more significant proportions in the analyzed samples and more infiltrated in the tumor microenvironment, the higher the expression of some of these resistance DEGs." (PMID 41234433, 2025). "Its mechanisms of action include inducing macrophages to polarize toward the pro-tumor M2 phenotype, promoting the differentiation of naive CD4+ T cells into Tregs, and weakening the cytotoxic functions of effector CD8+ T cells and NK cells." (PMID 41514551, 2025). "Strikingly, almost all CD4+ T cells inside the tumor express at least CD39 alone but mostly in combination with CD73." (PMID 39751916, 2025). "A total of 24 kinds of immune cells were significantly different in infiltration level between tumor and normal samples, except for central memory CD4 T cells, regulatory T cells, CD56 bright natural killer cells, and neutrophils." (PMID 41007849, 2025). "In GC tumor-bearing mice, the combination of a PD-1 inhibitor and apatinib significantly increased CD4+ and CD8+ T cell infiltration in the TME, while reducing MDSCs, thereby boosting the effectiveness of immunotherapy." (PMID 39967656, 2025). "This phenotype enables apCAFs to present processed antigens to CD4+ T cells within the tumor microenvironment, thereby establishing direct antigen-specific interactions." (PMID 40940809, 2025). "After sorting CD4+T cells by flow cytometry, we co‐cultured them with tumor cells according to the illustrated treatment." (PMID 39783838, 2025). "When we compared the proportion of PD-1+ cells between Meq+ cells and Meq− cells, the proportion of PD-1+ cells was significantly higher in Meq+ CD4+ T-cells than in Meq− CD4+ T-cells in the spleen and tumor tissues of chickens with MD." (PMID 40430752, 2025). "In non-tumor cell types, only the fraction of CD4+ T cells showed a marginally significant difference." (PMID 39649843, 2025). "Newly-infiltrating TAMs were most affected by PD-L1 blockade, which attenuated the rapid loss of inflammatory gene expression upon monocyte entry into the tumour and established self-potentiating IFNγ-driven responses between TAMs and CD4+ T cells." (PMID 40523200, 2025).
tumor (continued). "Tumours with high levels of MIR205HG were enriched for CD4 T cells and NK cells, on contrary MIR205HGlow tumours had a higher proportion of M2 macrophages." (PMID 40461454, 2025). "In the case of CD4+ cells, the landscape is a little bit more complex, since CD4+ T cells within the tumor can promote or suppress antitumor responses through the recognition of specific antigens." (PMID 40573917, 2025). "Tumor-T cell contact can activate cAMP pathways to trigger CD4+ T cell senescence, a process reversed by tumor cell TLR8 activation." (PMID 40860134, 2025). "Since the increase of TA-HEVs relies on Fc-dependent mechanisms during anti-CTLA-4 therapy, we next examined how an Fc-enhanced version of 9D9 (mouse IgG2a Fc) would modulate tumor-infiltrating CD4+ T cells and TA-HEVs." (PMID 40460830, 2025). "We thus utilized a highly innovative co-culture system to test how OC patient CD4+ T cell functions are regulated in OC tumor environment." (PMID 40872773, 2025). "In CRC, alterations in CD4+ T-cell responses, including subset distribution and functional adaptability, reshape the equilibrium between tumor-promoting and tumor-suppressive immunity in accordance with the prevailing inflammatory context." (PMID 41320679, 2025). "CD3 and CD4 provided prolonged tumor T1 relaxation and retained contrast for over 60 min, outperforming Gd-DTPA, which exhibited rapid signal decay." (PMID 41304872, 2025). "RCQ also suppressed tumor-infiltrating lymphocytes from becoming immunosuppressive populations, converting CD4+ T cells to Th2 cells, TANs to N2 cells, and TAMs to M2 cells." (PMID 40940890, 2025). "OC patients with high frequencies of either tumor-infiltrating CD127+ CD4+ T cells or blood-circulating 4-1BB+ CD4+ T cells showed significantly reduced PFS and OS, respectively." (PMID 41221283, 2025). "During the transition from a normal to a tumor state, increased interactions between M0 macrophages and naïve CD4+ T cells were observed." (PMID 40539072, 2025). "For example, abnormal blood vessels help tumors escape the attack of the immune system, Endostar normalizes abnormal tumor blood vessels, increases the infiltration of immune effector cells, and increases CD4+ or IL-2, which proves immunity." (PMID 39928822, 2025). "In vivo experiments further confirmed that Hmgb2flox/flox;Cd4-Cre mice combined with PD-1 antibody maximally attenuated tumor progression and promoted the infiltration of TEFF with killing function." (PMID 40315321, 2025). "The results revealed a higher infiltration level of tumor-suppressive immune cells, such as activated CD4+ T cells whereas tumor-promoting immune cells, such as mast cells and macrophages, exhibited lower infiltration levels." (PMID 40406134, 2025). "CD4+ T cell depletion markedly suppressed CT26-mock tumor growth, with complete regression observed in four out of five mice, whereas CD8+ T cell depletion promoted tumor growth." (PMID 40558520, 2025). "Gene Ontology (GO) enrichment analysis further indicated that pathways related to T cell function and anti-tumor cytotoxicity in CD4 and CD8 effector cells were enriched in the vaccine group." (PMID 40122855, 2025). "CD4+ T cells require appropriate activation in vivo for tumor clearance, as naïve CD4+ T cells cannot differentiate into tumor-specific CD4 effector cells." (PMID 40574005, 2025). "On one hand, anti‐tumour responses can be enhanced by CD4+ T cells, including Th1 and Th17 cells, through the secretion of cytokines such as IFN‐γ and IL‐17, which activate the immune system." (PMID 40785042, 2025). "Considering both cluster- and individual sample-based analyses, similar distribution patterns were observed, with slightly higher levels of NK cells (Pop 15) and CD8+ T cells (Pop 8), and lower levels of CD4+ T cells (Pop 12) in tumor samples." (PMID 41221282, 2025).
tumor (continued). "Remarkably, MET expression exhibited strong positive correlations with the abundance of tumor-infiltrating immune cells, including CD4+ T cells, CD8+ T cells, neutrophils, and macrophages (all P < 0.0001)." (PMID 41233563, 2025). "Recent studies have found that the intestinal flora Akkermansia muciniphila restores the efficacy of PD-1 blockade by increasing recruitment of CCR9+ CXCR3+ CD4+ T lymphocytes to mouse tumor beds in an IL-12-dependent manner." (PMID 38790057, 2024). "The increase in the infiltration of T cells was also demonstrated morphologically by immunohistochemistry, where the number of both CD8+ and CD4+ T cells was substantially increased in tumor tissue sections of MH-treated mice." (PMID 38444857, 2024). "In contrast to the findings in CD8+ T cells, peripheral CD4+ T cells showed functional alterations that were detrimental to tumor suppression." (PMID 38735538, 2024). "Focusing on immune cells, we observed an enrichment of several immune cell types, such as central memory CD8 T cells (CD8 TCm) (p-value = 0.074, adjusted for MES), CD4 naïve T cells (p-value = 0.042, adjusted for tumor cellularity) in r-HGP." (PMID 38548918, 2024). "Functionally, this cytokine is classified as pro-inflammatory, as it elicits the differentiation of CD4+ Th1 T cells, promotes the development of cytotoxic CD8+ T cells, induces NK cells and NK T cells, and concurrently suppresses tumor-associated macrophages." (PMID 39204319, 2024). "Meanwhile, adjuvants for peptide vaccines are essential for eliciting robust anti-tumor CD4+ T-cell responses." (PMID 39204073, 2024). "A 2Gy total body irradiation in mice primed the CD4+ T cell population to a higher tumor infiltration, characteristic of Th1 phenotypes." (PMID 39286254, 2024). "They further observed that expression of the neoantigen that harbors the MHC II–presented neoepitope is required in the tumor microenvironment for the CD4 response to be effective." (PMID 38426497, 2024). "Neoantigen-based personalized vaccines demonstrate significant immunogenicity and safety in GBM, generating robust CD8+ and CD4+ T cell infiltration into the tumor." (PMID 38610954, 2024). "In their hands, synthetic peptide vaccines consisting of a minimal CD8+ T cell epitope and either a CD4+ T cell neo-epitope or universal helper peptide PADRE protected equally well against a subsequent tumor challenge." (PMID 39040850, 2024). "For this purpose, we depleted CD4+ or CD8+ T cells in D4M tumor-bearing mice by injection of specific antibodies." (PMID 38631706, 2024). "Functional studies revealed that both tumor and non-tumor BTLA + CD4 + T-cells exhibited reduced capacity for IFNγ production compared to BTLA-CD4 + T-cells." (PMID 38233898, 2024). "The expression of the VDR is associated with the presence of several immune cell types, including B cells, CD8+ T cells, CD4+ T cells, macrophages, neutrophils, and dendritic cells, as well as the purity of tumor cells in CESC." (PMID 39268267, 2024). "The study also revealed that high HP1γ expression was negatively correlated with the levels of tumor-infiltrating lymphocytes (TILs), including B cells, CD4+ and CD8+ T cells, neutrophils, macrophages, and DCs." (PMID 39519018, 2024). "Through single‐cell sequencing, the remodeling of the tumor immune microenvironment induced by these new Arf1 inhibitors is analyzed and an increase in tumor‐associated CD8+ CD4+ double‐positive T (DPT) cells is identified." (PMID 39225354, 2024). "The levels of tumor‐infiltrating CD4 + cells, CD8 + T cells, dendritic cells, macrophages, NK cells, and plasma cells were substantially linked to FCGBP expression (all p < 0.05)." (PMID 38396056, 2024). "Gsdmc-WT expression decreased the tumor infiltration of Tregs, while increasing that of activated DC and CD4+ T cells, compared with Gsdmc-mut or vector in 4TO7-Brca–KO tumors." (PMID 37883181, 2024).
tumor (continued). "In general, cDC2s play important roles in the immune system during carcinogenesis by presenting tumor antigens to stimulate and activate CD4+ T cells, which are crucial for initiating and regulating immune responses." (PMID 39432076, 2024). "We have shown that iron levels significantly positively correlated only with the expression of CD4+ CD69+ lymphocytes T (p = 0.014) and CD4+ CD25+ T lymphocytes (p = 0.023) in tumor samples and CD3+ CD25+ T lymphocytes (p = 0.018) in node samples." (PMID 38256645, 2024). "We identified that mice therapy responders displayed significantly increased frequency of anti-tumor immune cells, such as CD4+ and CD8+ T cells, antigen-presenting dendritic cells, myeloid cells, and a trend for increased frequency for NK cells." (PMID 38893183, 2024). "These experiments demonstrated for the first time that MB tumor cells can function as direct CD4 T-cell suppressors." (PMID 39123357, 2024). "In young mice with MC38 tumors, anti-PD-L1 therapy can increase the infiltration and function of tumor-infiltrating CD8+ T cells, CD4+ Tcon cells, and tumor antigen-specific CD8+ T cells, resulting in a robust antitumor response." (PMID 38725070, 2024). "Considering the published report demonstrating the anti-tumor effects of apCAFs in NSCLC through direct activation of CD4+ effector T cells, we next examined the relationship between apCAFs and CD4+ effector T cells across various types of solid tumor." (PMID 38903527, 2024). "Tumor tissues contained CD4+ T lymphocytes, macrophages, and Tregs, whereas non-tumor samples contained primarily MAIT cells." (PMID 39410050, 2024). "Further phenotyping of T cells revealed that C002 tumor treatment increased both CD4(+) T cell frequency and absolute number, with a concomitant decrease in the CD8(+) frequency, resulting in an increased CD4: CD8 ratio." (PMID 38895115, 2024). "The obtained results revealed that the high-risk group exhibited a higher prevalence of M0, M1, and M2 macrophages, activated memory CD4 T cells, resting NK cells, resting mast cells, and neutrophils, along with higher tumor purity and lower immune scores." (PMID 38672263, 2024). "Our data showed that the CD8+ TILs/CD4+CD25+FOXP3+ Treg ratio was associated with improved OS and inversely correlated with tumor invasion and metastasis, suggesting that immune balance affects prognosis." (PMID 39264227, 2024). "Noteworthily, HPV+ OPSCC tumor cells embrace extensive intercellular communications with CXCL13+CD4+ T cells." (PMID 39105803, 2024). "In the tumor microenvironment, the treatment increased the percentage of memory T cells and innate effector cells and decreased CD4+ cells and regulatory T cells." (PMID 39126001, 2024). "Tregs represent a subset of CD4+ T cells whose increased activity in HCC facilitates tumor invasiveness and compromises T-cell immune responses through diverse mechanisms." (PMID 38791916, 2024). "The traditional Chinese medicine Jianpi Huayu Decoction has also been found to promote MDSC differentiation into macrophages and dendritic cells in mice with HCC, leading to enhanced CD4+ T cell proliferation and tumour regression." (PMID 38464388, 2024). "This interaction also influenced the CD4+/CD8+ ratio in the spleen while promoting IFN-γ-expressing CD8+ T cells in tumor tissues." (PMID 39690423, 2024). "The gene expression of Cd4 and Cd8 was also reduced in the tumor tissue, and the expression of αSma was increased in KO tumors." (PMID 38942797, 2024). "Conversely, CD4+ T cells (red) were more widely distributed, extending from the meninges (white arrows) to the tumor stroma (yellow dotted line), yet similarly clustered in the regions where TIBs were clustered (blue dotted line)." (PMID 39594720, 2024). "The results showed that anti-CAIX G36 BBζ CAR-T cells with a CD4/CD8 ratio of 2:1 demonstrated complete tumor regression and exhibited decreased exhaustion genes revealed by single-cell RNA sequencing (scRNAseq)." (PMID 38195534, 2024).
tumor (continued). "The visualization results of overall information flow revealed that the information flow from CXCL10+ M1 macrophages and CD4+T cell was significantly increased in the tumor group." (PMID 39170612, 2024). "The cytotoxic activity of CD8+ T cells is a potent effector mechanism in tumor destruction, while CD4+ T cells are pivotal in initiating and coordinating innate and antigen-specific immune response." (PMID 39569192, 2024). "The exact role of CD4 on monocytes in tumor development depends on the specific tumor type and individual differences among patients." (PMID 38566827, 2024). "Representative images from three patients (Pts 1, 6, and 15) at both pre- and post-treatment time points showed a marked increase in CD4 T cell infiltration into the tumor following AK104 treatment." (PMID 38280003, 2024). "Surprisingly, the percentage of CD8 and CD4 tumor-infiltrating lymphocytes (TILs) was much higher in growing (C-100) than eradicated (C-225) tumor." (PMID 39055715, 2024). "We found a driver role for A. temperans in tumor growth whereby bacterial instillation increased tumor growth through inflammation, primarily driven by neutrophils, macrophages, and CD4+ T cells." (PMID 38570533, 2024). "In particular, CCR2+ myeloid cells are recruited into the tumor bed and a CD4+ T cell-mediated response stimulates macrophages to clear pre-malignant SnCs." (PMID 38561826, 2024). "Three multi-antigen DNA vaccines were designed that induced neoantigen-specific CD8+ T cell responses only (noHELP) or together with CD4+ T cell responses to either tumor-unrelated “universal” antigens (uniHELP) or MC-38-derived neoantigens (neoHELP)." (PMID 39040850, 2024). "This observed treatment effect is characterized by a higher percentage of activated tumor-infiltrating CD4+ and CD8+ T cells, coupled with a reduction in exhaustive lymphocyte activity." (PMID 38675812, 2024). "The intrinsic capacity of B cells to specifically activate tumour-specific CD4+ T cells invivo via TCR-dependent interactions remains poorly defined." (PMID 38125720, 2024). "The Ciborsort analysis similarly indicated that high-risk individuals had diminished infiltration of critical anti-tumor immune cells such as Cytotoxic T cells, CD4+ T cells, and NK cells." (PMID 39569192, 2024). "Local cytokine delivery enhanced CD8+ T cell numbers and reduced CD4+CD25+ Tregs in the tumor draining LN." (PMID 38803496, 2024). "In terms of tumor immune infiltration, CDC45 was significantly associated with B cell, CD8 + T cell, CD4 + T cell, neutrophil, dendritic and macrophage cell infiltration (all p < 0.001)." (PMID 37642814, 2024). "Depletion of Tregs promotes tumour growth, as demonstrated by Noy and Pollard’s research: CD4+ Tregs are immune-suppressive, directly reducing the ability of CD8+ cytotoxic T cells to fight tumours by secreting IL-10 and transforming growth factor β." (PMID 38339377, 2024). "This pattern was also observed for the TPK1 tumour cells and both CD4 + FOXP3 and CD8 + CXCL13 + ITGAE immune cells in the high-score group." (PMID 38730464, 2024). "Since most FoxP3+ cells also express CD4, this indicates that the proportion of regulatory T cells versus helper T cells increased during tumor progression." (PMID 38812785, 2024). "CXCL9/10/11 are interferon-induced chemokines that recruit effector CD8+ and CD4+ T cells to the tumor microenvironment by binding them to their cognate receptor CXCR3." (PMID 38928238, 2024). "Overall, this data suggests that CD4+ T cells have a prominent cytotoxic role in anti-tumor immunity in MMRd tumors (including MHC-I proficient ones) more than previously anticipated." (PMID 39544936, 2024). "CD4+ T cells from peripheral and non-tumor tissues expressed lower levels of granzyme B and perforin than paired circulating CD4+ T cells." (PMID 38335302, 2024).